CCNJL (cyclin J like)
Synonyms: FLJ14166
Tractability: No criterion of Open Targets' tractability assessment is met for any kind of drug.
Gene: Protein-coding gene on chromosome 5 (160,249,083 to 160,345,396, reverse strand). Ensembl gene ENSG00000135083.
Subcellular location (Human Protein Atlas): Nuclear speckles
Gene Ontology:
Molecular function: protein binding; cyclin-dependent protein serine/threonine kinase regulator activity
Cellular component: cyclin-dependent protein kinase holoenzyme complex; microtubule organizing center
Genetic constraint (gnomAD): Loss-of-function variants: 33 observed, 34.94 expected, observed/expected ratio (o/e) 0.94, 90% interval 0.71 to 1.26. The upper end of that interval is the gene's LOEUF score, 1.26, which puts it in group 5 of 6, group 1 being the genes least tolerant of losing a copy. Missense variants: 512 observed, 512.61 expected, observed/expected ratio (o/e) 1, 90% interval 0.93 to 1.08. Synonymous variants: 227 observed, 226.06 expected, observed/expected ratio (o/e) 1, 90% interval 0.9 to 1.12.
Homologues: Orthologues: chimpanzee CCNJL (99% identical), macaque CCNJL (98% identical), rat Ccnjl (90% identical), pig CCNJL (89% identical), dog CCNJL (89% identical), guinea pig CCNJL (89% identical), mouse Ccnjl (88% identical), rabbit CCNJL (87% identical), zebrafish ccnjl (48% identical), Caenorhabditis elegans cyd-1 (16% identical), Caenorhabditis elegans cye-1 (15% identical), Caenorhabditis elegans cyb-1 (14% identical), and 5 more. Paralogues in human: CCNJ (43% identical), CCNA2 (17% identical), CCNA1 (16% identical), CCNB1 (16% identical), CCND1 (16% identical), CCNB2 (16% identical), CCND2 (15% identical), CCNE1 (15% identical), CCNI (15% identical), CCND3 (15% identical), CCNG1 (15% identical), CCNE2 (14% identical), and 6 more.
Diseases named in the same sentence as CCNJL in open-access papers:
CCNJL is named in the same sentence as 4 diseases in open-access papers, as found by Europe PMC text mining. Sharing a sentence is not in itself a finding about the gene and the disease. The quoted sentences say what the papers report.
colon cancer (1 paper, 2021). "In this study, we identified six cyclin genes (CCNA2, CCNB1, CCND1, CCNE1, CCNF, and CCNJL) that are potential diagnostic biomarkers of colon cancer." (PMID 33996604, 2021). "Among the four datasets of colon cancer from The Cancer Genome Atlas and the Gene Expression Omnibus, six cyclin genes (CCNA2, CCNB1, CCND1, CCNE1, CCNF, and CCNJL) were differentially expressed between normal and tumor tissues." (PMID 33996604, 2021). "Consistently, CCNA2, CCNB1, CCND1, and CCNF have been observed to be upregulated in colorectal cancer, but there is no clear evidence that CCNE1 and CCNJL are also differentially expressed between colon tumor and normal tissues." (PMID 33996604, 2021).
hepatocellular carcinoma (1 paper, 2021). A malignant tumor that arises from hepatocytes. "CCNJL expression is inversely correlated with survival in hepatocellular carcinoma." (PMID 34090518, 2021).
tumor (1 paper, 2021). "In this study, the differential expression analysis showed that among all cyclin family members, there were six significant DEGs (CCNA2, CCNB1, CCND1, CCNE1, CCNF, and CCNJL), five of which were overexpressed in tumor samples compared to normal controls, while CCNJL was downregulated." (PMID 33996604, 2021). "Among them, the curve of CCNJL in GSE41258 contrasted with that in the other two datasets, possibly because CCNJL expression was relatively lower in tumor tissues, which led to inaccuracies." (PMID 33996604, 2021).
CCNJL also shares sentences with these, for which no sentence is quoted: colorectal cancer (1 paper).